IL6 (interleukin 6)
Diseases named in the same sentence as IL6 in open-access papers (continued):
Sharing a sentence is not in itself a finding about the gene and the disease.
cancer (continued). "However, the previous clinical study on cancer patients did not examine the relationship between IL-6 and resolution-related molecules." (PMID 32117207, 2019). "Extensive research on this part of the fruit may be of great interest due to its anti-inflammatory properties (decreasing the generation of interleukin-6 pro-inflammatory mediators, IL-6; and prostaglandin-E2, PGE2; anti-cancer, antioxidant, and antihypertensive factors)." (PMID 31731548, 2019). "Moreover, some studies have revealed that IL-6 and HGF could help cancer cells to acquire the ability of anoikis resistance, suggesting bypass signaling in the EGFR pathway may play a significant role in anoikis resistance." (PMID 31198634, 2019). "Hence, IL-6 and MCT-1 collaboratively advance cancer stemness." (PMID 30885232, 2019). "The PTX-resistant phenotype in BCA showed the increased multi-drug resistant genes and cytokines including IL-6 and IL-8 compared to PTX-sensitive BCA cells indicating that the PTX resistant phenotype had developed changes in gene expression that might promote cancer progression." (PMID 29486738, 2018). "Furthermore, our analysis reveals that toxin may affect IL6-expression via a number of mechanisms, including JAK-STAT cascade, cytosolic DNA-sensing, TNF signaling pathway and transcriptional misregulation in cancer cells." (PMID 29593668, 2018). "In addition, the cancer cell-derived osteoclast-activating factors MCSF, IL-6, IL-8, RANKL, MMP2, MMP13, RUNX2 and PTHrP are significantly down-regulated in MDA-MB-231 cells transfected with miR-124 mimic and up-regulated in MCF7 cells transfected with miR-124 inhibitor." (PMID 29343249, 2018). "Moreover, Choi and colleagues reported that açaí treatment down-regulated myeloperoxidase (MPO) and proinflammatory cytokines (TNF-α, IL-1β and IL-6), inhibited cyclooxygenase 2 (COX-2), PCNA and Bcl-2, and increased Bad and cleaved caspase-3 expression in an experimental model of cancer colon." (PMID 29966007, 2018). "However, increased IL-6 secretion has also been reported for some cancer cells, particularly those that are not dependent on autophagy for survival." (PMID 30622432, 2018). "Interestingly, the only influential parameter not related to CSCs and IL-6 is the maximum death rate of the terminally differentiated cancer cells." (PMID 29351275, 2018). "Doing a differential expression between the two clusters of cancer fibroblasts, we found metastatic fibroblasts were found to express higher levels of soluble factors compared to primary fibroblasts including, CXCL12, S100A6, S100A10, SFRP2,SFRP4,IGF1, CXCL14, ANGPTL4 and IL6." (PMID 30383866, 2018). "Indeed, it has been reported that increased inflammatory cytokines, such as IL-6, might be involved in the enhanced phosphorylation of STAT3 in muscle tissue of cancer cachexia model." (PMID 30555329, 2018). "Secondly, IL-6 could activate PI3K/Akt pathway and thus promote cancer cell survival." (PMID 30013512, 2018). "EOs showed significant cytotoxic effects on cancer cell lines (IC50 0.007 to >0.1%), with a reduction in cell viability with up to 90% at a concentration of 0.1%, and anti-inflammatory activity (IC50 0.0008–0.02%) with a reduction of IL-6 secretion with up to 60% at a concentration of 0.01%." (PMID 28385055, 2017). "Furthermore, the oncogenic dysregulation of the RAS, MYC and the MAPK pathways in cancer cells are known to induce the production of growth factors and cytokines such as VEGF, IL-6, IL-10, and IL-1β, leading to the recruitment and the tumorigenic transformation of macrophages." (PMID 28969664, 2017). "Moreover, IL6 production from UC cells might play a key role in the induction of TAM and the protection of the cancer cells from BCG treatment." (PMID 29048388, 2017).
cancer (continued). "In this study, we did not observe positivity for cancer stem cells with markers such as CD133, OCT4, or Nanog (data not shown), suggesting that rising or re-populating of cancer stem cells is not the major mechanism by which IL-6 induces prostate tumorigenesis in current model." (PMID 28077171, 2017). "In addition, serum IL-6 is elevated in SCLC in relationship with advanced stages, worse prognosis and Neuron Specific Enolase (NSE) levels, suggesting a possible role of IL-6 in SCLC progression, similarly to other cancers." (PMID 29020964, 2017). "We propose that in cancer cachexia, increased FoxO3 occupancy at pro-atrophic genes MuRF1, MAFbx/Atrogin-1, and GABARAPL1 is promoted by AMPK-mediated FoxO3 phosphorylation, which is ultimately induced by increased systemic IL6 levels and AMPK activation in skeletal muscle." (PMID 29167426, 2017). "However, although IL-6 did not change during cancer treatment, the symptom cluster was associated with both TNF-α and IL-6, suggesting that only part of the inflammation leading to symptom experience was due to treatment." (PMID 28616125, 2017). "Furthermore, it has been further demonstrated that, when macrophages were cocultured with MCF-7 cells suffering apoptosis, they secreted IL-6, activating STAT3 phosphorylation, and therefore performed a role on the activation of cancer stem cells and cancer promotion." (PMID 28970834, 2017). "Notably, the evaluation of the mean fluorescence intensity of the cancer cells and a histological examination revealed that the OSK-A549-Colony cell-derived organoids were sensitive to the combination of cisplatin and anti-IL-6 antibodies (1 μg/ml)." (PMID 28951614, 2017). "Similarly, the expression level of IL-6 was also significantly higher in the cancer tissues compared with adjacent non-cancerous tissues." (PMID 28186964, 2017). "By itself, IL-6 might endow cancer stem cells with migratory phenotype via EMT without necessarily acting as chemokine to induce cell movement." (PMID 29245982, 2017). "Considering heterogeneous malignancies, it's suggested that the level of IL-6 expression might play a different important role at the step of each cancer progression, although the reasons for this have not been understood." (PMID 28548958, 2017). "In conclusion, we found that BMSCs may activatethe IL-6/STAT3 signaling pathway and promote cell invasion in Bel-7404cells, suggesting that this protumor effect should be seriously consideredbefore clinical application of MSC-mediated cancer therapy." (PMID 28659496, 2017). "In addition to IL-6, STAT3 can be activated by EGFR in many cancer types." (PMID 29262529, 2017). "Tailoring the AAb profiling with a systems biology approach provides an excellent image of the network of AAbs targeting proteins which may be key drivers of cancer-interacting SPs such as PLD, PI3K-Akt, MAPK, EGF/EGFR, c-Met, Ras, DDR, IL-4, IL-6, and TGF-β SPs in the NSCLC and SM groups." (PMID 29062084, 2017). "Although wide variations in SASP expression existed across PTC cases, the expression of interleukin (IL)-6, IL-8 and matrix metalloproteinases (MMPs) was markedly upregulated in cancer tissue as compared with levels observed in corresponding non-neoplastic thyroid tissues." (PMID 28489070, 2017). "We then hypothesized that SOM230, by affecting protein synthesis in CAFs, and subsequently the composition of their CM (including IL-6 concentration), indirectly inhibits epithelial-to-mesenchymal transition (EMT) in cancer cells, a critical process for cancer cell migration and invasion." (PMID 27177087, 2016). "Celecoxib also inhibited cancer cell migration towards conditioned media of proliferating fibroblasts to a greater extent than its senescent counterparts indicating the presence of other COX-2 and IL-6 independent SASP components in the conditioned media of senescent fibroblasts." (PMID 27385366, 2016).
cancer (continued). "In this study, our results suggest that CAF ERα could be applied as a prognostic marker to predict cancer progression, and targeting CCL5 and IL6 may be applied as an alternative therapeutic approach to reduce M2 type macrophage and PCa invasion in CAF.ERα(−) PCa patients." (PMID 26790618, 2016). "IL-6 and IL-8 can further activate STAT3, which has been shown to promote apoptotic resistance and contribute to poor prognosis of cancer patients Although TRAF6 is known to mediate LPA-stimulated NF-κB activation, it is not clear whether TRAF6 plays a particular role in the LPA2 receptor signaling." (PMID 27134758, 2016). "IL‐6 has been shown to induce the activity of AR 46, 47, and therefore the effect of palcar in inducing IL‐6 in PC3 cells may suggest a potential role of this class of compounds in promoting cancer proliferation." (PMID 27403764, 2016). "Our data suggest that CAF ERα could be applied as a prognostic marker to predict cancer progression, and targeting CCL5 and IL6 may be applied as an alternative therapeutic approach to reduce M2 type macrophages and PCa invasion in PCa patients with low or little ERα expression in CAF cells." (PMID 26790618, 2016). "However, the median IL-6 level in patients with advanced stage IV cancer was not significantly different than in patients with stage I, II and III." (PMID 26148092, 2015). "However, LIF secretion may be stimulated by pro-inflammatory cytokines, such as IL-6, IL-1 and tumor necrosis factor (TNF)-α, leading to elevated serum LIF levels in cancer patients." (PMID 26296968, 2015). "Compared to DVT- cancer patients, DVT+ showed an increased fold change of 1.28 (95% CI: 1.20–1.37; p<0.0001), 1.34 (95% CI: 1.23–1.46; p<0.0001), 1.41 (95% CI: 1.30–1.54; p<0.0001), and 1.61 (95% CI: 1.45–1.78; p<0.0001) for IL-6, TNF-α, Il-1β, and VEGF, respectively." (PMID 26192925, 2015). "Moreover, activated platelets contain significant quantities of IL-6 and secrete factors such as vascular-endothelial growth factor (VEGF) and other factors that promote angiogenesis and may prevent recognition of cancer cells by the body’s own immune system." (PMID 26544968, 2015). "Although the use of IL-6 inhibitors has not been explored in PDT research, cancer-related studies in which IL-6 signaling was inhibited may provide clues as to the potential (neo)adjuvant efficacy of IL-6 inhibitors for the enhancement of PDT." (PMID 26516076, 2015). "Our results suggest a potential role for PCT and IL-6 in predicting cancer in non-febrile patients." (PMID 26148092, 2015). "IL-6 levels were measured in control patients and non-febrile cancer patients." (PMID 26148092, 2015). "Overall, we suggest that a rational design of cancer immunotherapy mediated by CD4+ T cells in the elderly can be administered concurrently with temporal neutralization of IL-6 activity to restore the defective Th1 development without adversely affecting their antitumour activities." (PMID 25850032, 2015). "However, following treatment with IL-6, the hUC-MSCs did not have a growth-promoting effect on gastric epithelial and cancer cells." (PMID 25483835, 2015). "IL-6 is often upregulated in epithelial cancers, such as breast and prostate and the IL-6/STAT3 axis is often considered as part of a positive regulatory circuit operating in inflammatory setting to nourish cancer cells and allow to maintain their transformed phenotypes." (PMID 25026286, 2014). "Furthermore, a variety of malignant tumors, including OSCC and adenocarcinomas were shown to contain or synthesize IL-6, and autocrine growth stimulation has been suggested as a possible mechanism for the action of IL-6." (PMID 24398980, 2014).
cancer (continued). "IL-6 is pro-inflammatory, promotes steatohepatitis and activates signal transducer and activator of transcription 3 (STAT3) in hepatocytes, and all three mechanisms may be related to cancer induction." (PMID 25533006, 2014). "Human and zebrafish genomes are 70% similar based on conservation of individual genes, with several cancer-associated genes found in mammals but not in the zebrafish, including BRCA1, p16 (CDKN2A), BRCA1, LIF, OSM, IL6 and PML (G.D. and J.N.B., unpublished observation)." (PMID 24973744, 2014). "Both the NF-κB/IL6/JAK2/STAT3 cascade, which we show here is modulated by miR-221/222-mediated downregulation of ADIPOR1, and ZEB2 expression, which we have previously shown is repressed by TRPS1, are well-characterized effector pathways in cancer metastasis, invasion, and EMT." (PMID 23776679, 2013). "In addition, depressed cancer patients display elevated levels of IL-6 relative to both non-depressed cancer patients and depressed non-cancer patients." (PMID 23594674, 2013). "Therefore, downregulation of IL-6 production by SME and APO-9′ may have potentials in anti-inflammatory and anti-cancer application." (PMID 23985898, 2013). "While IL-6 and TNF-alpha receptor antagonists are now used clinically for the treatment of a wide range of rheumatological or hematological disorders, it will be of interest to follow-up on patients treated with such agents for any potential beneficial effects on cancer development." (PMID 24205276, 2013). "IL-6 has been shown to induce STAT3 phosphorylation and may play a role in cancer development." (PMID 23056374, 2012). "Thus, macrophage-derived cytokines, such as IL-6 and TNF-α, might be promising therapeutic targets for cancer cachexia." (PMID 23326296, 2012). "However, IL-6 expression level in cancer cells was not altered by the treatment with hochuekkito by immunohistochemical analysis." (PMID 23326296, 2012). "In addition, control cancer cells expressed more epithelial-to-mesenchymal transition (EMT)-related molecules such as N-cadherin and vimentin, compared with either TG2-knocked-down (shTG2_MB231#1) or IL-6-knocked-down cells (shIL-6_MB231#6)." (PMID 21967801, 2011). "Consistent with previous literature, we found that drug resistant cancer cells secreted more IL-6 secretion than the parental cells, and not only NF-κB, PI3-K/Akt and MEK/Erk but also Jak2/Stat3 pathway contributed to the autocrine production of IL-6 in these cells." (PMID 21122157, 2010). "Thus, changes of co-expression of these shared neighbours with either IL2 or IL6 might disrupt the Jak-STAT signalling pathway and contribute to the progression of cancer." (PMID 21059271, 2010). "However, recent reports highlighted the intimate involvement between cancer progression and IL-6 trans-signaling through sIL-6R, rather than the classical IL-6 signalling pathway through IL-6R." (PMID 20823887, 2010). "Another important study investigating the possible effect of Stat3 on immune suppression of cancer cells found that the inhibition of Stat3 with antisense oligonucleotide and with dominant-negative form of Stat3 (Stat3β) resulted in an increase in IL-6 in mouse cancer cells." (PMID 21122157, 2010). "In addition to IL-6, the expression of cyclin D1, c-myc, survivin, Bcl2, Mcl1, and VEGF, all of which are regulated by Stat3 activity, and play a crucial role in apoptosis and progression of cancer, are also down regulated in response to avicin D." (PMID 19440292, 2009). "Similarly, in the cancer group with detectable interleukin-6 concentrations, they were not significantly altered (P=0.869) over the feeding period." (PMID 15026790, 2004). "Furthermore, ω-3 PUFAs have been shown to modulate inflammatory cytokines, notably interleukin-6 (IL-6) and tumor necrosis factor-α (TNF-α), both of which play pivotal roles in carcinogenesis and disease progression, supporting their potential therapeutic application in cancer management." (PMID 41515289, 2026).
cancer (continued). "Because differences in cancer stem cell frequencies exist between highly and low-tumorigenic BrCa cells, exploring whether O-GlcNAcylated CTCF regulates the 3D chromatin shape in the IL6 gene across BrCa cells with different stem cell proportions warrants further investigation." (PMID 40143084, 2025). "Compounds MJ2, MJ8, MJ15, and MJ19 had a stronger effect on the expression of the BCL2, MDM2, AIFM2, IL6, and IL8 genes in the healthy BEAS-2B cell line than in the cancerous HCT116 cell line, which may indicate their potential protective effect on normal cells with limited effect on cancer cells." (PMID 40725171, 2025). "The use of inflammatory parameters, such as IL-6, tumor necrosis factor alpha (TNF-α), and CRP, allows for a simple and rapid evaluation of whether IF effectively reduces chronic inflammation—a factor known to be involved in the initiation and progression of cancers." (PMID 41008741, 2025). "Furthermore, bioinformatic analysis of miR‐34a targets in various cancers identifies numerous target genes such as Jagged 1 (JAG1), CD44, SRY (sex determining region Y)‐box 4 (SOX4), Notch homolog 2 (NOTCH2), Matrix metallopeptidase 9 (MMP9), Interleukin 6 (IL‐6), and SMAD family member 4 (SMAD4)." (PMID 40336533, 2025). "In endothelial cells and monocytes stimulated with TNF-α to mimic sepsis, caprylate enhanced mitochondrial respiration without increasing IL-6 secretion, suggesting that it may influence energy metabolism in cancer and normal tissues without promoting pro-inflammatory signaling." (PMID 41003013, 2025). "Moreover, it was confirmed that MSCs recruited from human cancers can actively increase the expression of immunosuppressive agents, i.e., IL-10, TGF-β1 and indoleamine 2,3-dioxygenase (IDO), and angiogenic factors, i.e., TGF-β1, VEGF, angiopoetin-1, endothelin-1, and IL-6." (PMID 39120301, 2024). "However, its role against IL-6 in any cell type, including cancer cells, has not been explored." (PMID 38338683, 2024). "This process involves an increase in inflaming cytokine release (Interleukin-6 (IL-6) and Plasminogen activator inhibitor-1 (PAI-1)) and may result in the transformation of non-malignant stromal cell types (fibroblasts and macrophages) into cancer-related fibroblasts and macrophages." (PMID 38899007, 2024). "However, trans-signaling is an alternative to the classic IL-6 signaling pathway and allows for the modulation of functions of a wide range of target cells (including cancer cells, neurons, or osteoclasts that do not have the membrane-bound receptor composed of alpha and beta subunits)." (PMID 38791322, 2024). "Moreover, long-term hyperglycemia leads to the production of pro-inflammatory factors such as IL-6, TNF- α, and cyclooxygenase-2 (COX-2) which may play a role in cancer development by stimulating oncogene expression, regulating cell cycle, and promoting cancer cell proliferation." (PMID 39410536, 2024). "Furthermore, IL-6 levels can be a negative prognostic indicator in cancer patients." (PMID 38611065, 2024). "Interestingly, IL-6-mediated activation and the phosphorylation of STAT3 enhances glycolytic effect in C26 colon cancer, which in turn amplifies EV secretion that can further contribute to the induction of skeletal muscle and adipose tissue atrophy, leading to the development of cancer cachexia." (PMID 37998333, 2023). "We did however find that WLWH with HPV infection had the highest level of IL-6 and CD8 + immune activation compared with SNW without HPV infection, reflecting a generalized state of chronic inflammation, which has been shown to be a risk factor for cancer development." (PMID 36658503, 2023). "In addition, cancer-promoted inflammation also plays a key role in determining CRC development, and inflammatory cytokines, such as interleukin-6 (IL-6) and IL-1, are significantly elevated in CRC patients, which could have an important role in supporting CCSCs." (PMID 36750842, 2023).